PIK3CB (phosphatidylinositol-4,5-bisphosphate 3-kinase catalytic subunit beta)
Description:
Phosphoinositide-3-kinase (PI3K) phosphorylates phosphatidylinositol derivatives at position 3 of the inositol ring to produce 3-phosphoinositides. Uses ATP and PtdIns(4,5)P2 (phosphatidylinositol 4,5-bisphosphate) to generate phosphatidylinositol 3,4,5-trisphosphate (PIP3). PIP3 plays a key role by recruiting PH domain-containing proteins to the membrane, including AKT1 and PDPK1, activating signaling cascades involved in cell growth, survival, proliferation, motility and morphology. Involved in the activation of AKT1 upon stimulation by G protein-coupled receptor (GPCR) ligands such as CXCL12, sphingosine 1-phosphate, and lysophosphatidic acid. May also act downstream receptor tyrosine kinases. Required in different signaling pathways for stable platelet adhesion and aggregation. Plays a role in platelet activation signaling triggered by GPCRs, alpha-IIb/beta-3 integrins (ITGA2B/ ITGB3) and ITAM (immunoreceptor tyrosine-based activation motif)- bearing receptors such as GP6. Regulates the strength of adhesion of ITGA2B/ ITGB3 activated receptors necessary for the cellular transmission of contractile forces. Required for platelet aggregation induced by F2 (thrombin) and thromboxane A2 (TXA2). Has a role in cell survival. May have a role in cell migration. Involved in the early stage of autophagosome formation. Modulates the intracellular level of PtdIns3P (phosphatidylinositol 3-phosphate) and activates PIK3C3 kinase activity. May act as a scaffold, independently of its lipid kinase activity to positively regulate autophagy. May have a role in insulin signaling as scaffolding protein in which the lipid kinase activity is not required. May have a kinase-independent function in regulating cell proliferation and in clathrin-mediated endocytosis. Mediator of oncogenic signal in cell lines lacking PTEN. The lipid kinase activity is necessary for its role in oncogenic transformation. Required for the growth of ERBB2 and RAS driven tumors. Also has a protein kinase activity showing autophosphorylation.
Synonyms: PI3Kbeta; p110beta; PIK3C1; PI3K
Tractability: Small molecule: a drug acting on it is in phase 2 or 3 trials; a high-quality ligand is known; it belongs to a druggable protein family. Antibody: its Gene Ontology location is reachable by antibodies, with medium confidence. PROTAC: ubiquitination databases record sites on it; its protein half-life has been measured; a small molecule that binds it is known.
Target class: Enzyme; Transferase
Chemical probes: APITOLISIB (high quality), AZD-6482 (high quality), GSK2358994, GSK2373693A, NVP-CRL-457, PD081522, PD082562, PD083034, PD083582, PD083798, PD084194, PD084214, PIK-108, TGX-221 (high quality)
Gene: Protein-coding gene on chromosome 3 (138,652,336 to 138,834,957, reverse strand). Ensembl gene ENSG00000051382.
Subcellular location: Cytoplasm; Nucleus
Subcellular location (Human Protein Atlas): Nucleoli; Nucleoplasm; Midbody; Vesicles
Pathways (Reactome):
Signal Transduction: Downstream signal transduction; Erythropoietin activates Phosphoinositide-3-kinase (PI3K); IRS-mediated signalling; PI3K Cascade; PI3K/AKT activation; PI5P, PP2A and IER3 Regulate PI3K/AKT Signaling; PIP3 activates AKT signaling; RAF/MAP kinase cascade; Signaling by ALK; Signaling by LTK; VEGFA-VEGFR2 Pathway
Immune System: CD28 dependent PI3K/Akt signaling; Co-stimulation by ICOS; DAP12 signaling; Downstream TCR signaling; Interleukin receptor SHC signaling; Interleukin-3, Interleukin-5 and GM-CSF signaling; Regulation of signaling by CBL; Role of LAT2/NTAL/LAB on calcium mobilization; Role of phospholipids in phagocytosis; Signaling by CSF1 (M-CSF) in myeloid cells
Disease: Constitutive Signaling by Aberrant PI3K in Cancer; Signaling by ALK fusions and activated point mutants; Signaling by LTK in cancer; Signaling by PDGFRA extracellular domain mutants; Signaling by PDGFRA transmembrane, juxtamembrane and kinase domain mutants
Hemostasis: GPVI-mediated activation cascade; Tie2 Signaling
Cell-Cell communication: Nephrin family interactions
Cellular responses to stimuli: High laminar flow shear stress activates signaling by PIEZO1 and PECAM1:CDH5:KDR in endothelial cells
Developmental Biology: RET signaling
Metabolism: Synthesis of PIPs at the plasma membrane
Gene Ontology:
Molecular function: 1-phosphatidylinositol-4,5-bisphosphate 3-kinase activity; protein binding; protein serine kinase activity; 1-phosphatidylinositol-3-kinase activity; 1-phosphatidylinositol-4-phosphate 3-kinase activity; insulin receptor substrate binding; kinase activity; protein serine/threonine kinase activity
Biological process: natural killer cell mediated cytotoxicity; negative regulation of phosphatidylinositol 3-kinase/protein kinase B signal transduction; negative regulation of sprouting angiogenesis; negative regulation of vascular endothelial growth factor signaling pathway; phosphatidylinositol 3-kinase/protein kinase B signal transduction; phosphatidylinositol phosphate biosynthetic process; positive regulation of endothelial cell migration; positive regulation of gene expression; positive regulation of neutrophil apoptotic process; positive regulation of nitric oxide biosynthetic process; positive regulation of Rac protein signal transduction; regulation of cell-matrix adhesion; sphingosine-1-phosphate receptor signaling pathway; cell migration; cell surface receptor protein tyrosine kinase signaling pathway; chemotaxis; G protein-coupled receptor signaling pathway; negative regulation of MAPK cascade; phosphatidylinositol-3-phosphate biosynthetic process; phosphatidylinositol-mediated signaling; platelet activation; platelet aggregation; positive regulation of autophagy; regulation of clathrin-dependent endocytosis; response to ischemia; and 5 more
Cellular component: cytoplasm; nucleolus; nucleoplasm; nucleus; phosphatidylinositol 3-kinase complex, class IA; cytosol; phosphatidylinositol 3-kinase complex; plasma membrane
Genetic constraint (gnomAD): Loss-of-function variants: 9 observed, 49.19 expected, observed/expected ratio (o/e) 0.18, 90% interval 0.11 to 0.32. The upper end of that interval is the gene's LOEUF score, 0.32, which puts it in group 1 of 6, group 1 being the genes least tolerant of losing a copy. Missense variants: 379 observed, 607.29 expected, observed/expected ratio (o/e) 0.62, 90% interval 0.57 to 0.68. Synonymous variants: 194 observed, 219.98 expected, observed/expected ratio (o/e) 0.88, 90% interval 0.78 to 0.99.
Cancer hallmarks: genome instability and mutations (suppresses); escaping programmed cell death (promotes)
Homologues: Orthologues: chimpanzee PIK3CB (99% identical), macaque PIK3CB (99% identical), rabbit PIK3CB (98% identical), pig PIK3CB (98% identical), dog PIK3CB (97% identical), rat Pik3cb (96% identical), mouse Pik3cb (95% identical), guinea pig PIK3CB (89% identical), tropical clawed frog pik3cb (77% identical), zebrafish pik3cb (69% identical), Drosophila melanogaster Pi3K92E (37% identical), Caenorhabditis elegans age-1 (27% identical), and 2 more. Paralogues in human: PIK3CD (56% identical), PIK3CA (40% identical), PIK3CG (31% identical), PIK3C2B (26% identical), PIK3C2A (26% identical), PIK3C2G (22% identical), PIK3C3 (21% identical), PI4KA (18% identical), PI4KB (13% identical).
Diseases named in the same sentence as PIK3CB in open-access papers:
PIK3CB is named in the same sentence as 99 diseases in open-access papers, as found by Europe PMC text mining. Sharing a sentence is not in itself a finding about the gene and the disease. The quoted sentences say what the papers report.
breast cancer (31 papers, 2012 to 2025). A primary or metastatic malignant neoplasm involving the breast. "The effects of acquired PIK3CB mutations in response to PIK3CA inhibition was studied in breast cancer cells after treatment with pictilisib." (PMID 40564038, 2025). "PTEN-null breast cancer cells were treated with pictilisib until they reached resistance and were sequenced to determine possible PIK3CB mutations." (PMID 40564038, 2025). "Despite this, the stable expression of mutant PIK3CB variants can be overcome by AKT or mTORC1/2 inhibitors in breast cancer cell lines." (PMID 38920692, 2024). "PIK3CB also exhibited significant diagnostic performance in differentiating breast cancer from healthy controls." (PMID 37861518, 2023). "FTO and PIK3CB demonstrated significant diagnostic performance for breast cancer, with FTO achieving a specificity of 90.63%." (PMID 37861518, 2023). "Recently, activation of PIK3CB gene encoding catalytic subunit p110β of PI3Kβ appears to be involved in the development of prostate and breast cancer." (PMID 33147762, 2020). "Evidence shows that genetic deletion of PI3KCA suppresses tumor formation of breast cancer, whereas loss of PIK3CB leads to mammary gland hyperplasia and tumorigenesis, accompanied by increased PI3K activity and Akt phosphorylation level." (PMID 27176481, 2016). "The most common event that leads to PI3Kβ-isoform signaling deregulation is PTEN deficiency, although PIK3CB amplification has been described in breast cancer." (PMID 23232172, 2012). "Interestingly, the genetic ablation of the protein encoded by PIK3CB was described to increase ductal branching and tumorigenesis and could lead to mammary gland hyperplasia in transgenic models of breast cancer." (PMID 28569218, 2017). "RNAi-based screening for synthetic lethal interactions with loss of PTEN in breast cancer identified NUAK1, along with STK11 and PIK3CB, suggesting functional interaction between the LKB1-NUAK1 and PI3K-AKT pathways." (PMID 38939918, 2024). "Amplification of the PIK3CA gene locus and other rare genetic alterations, such as PIK3CB amplification or PIK3R1 inactivating mutations, have been identified, further highlighting the complexity of this pathway’s involvement in breast cancer." (PMID 39850811, 2024). "Exosomal circ 0001142 promoted the M2 polarization of macrophages and increased the proliferation and metastasis of breast cancer cells via the miR-361-3p/PIK3CB axis." (PMID 38523627, 2024). "In luminal breast cancer, PIK3CB, ACVR18, HGF, and ERG were identified as the key genes with varying mutation frequencies between the luminal HER2-low and luminal HER2-0 subgroup." (PMID 39648226, 2024). "Then, we evaluated the diagnostic value of FTO, PIK3CB, CEA, and CA15-3 alone and in combination for breast cancer." (PMID 37861518, 2023). "miR-301b also targets PIK3CB (P110-β), the catalytic subunit of PI3Kβ, which has been shown to enhance cell proliferation and promote tumorigenesis in breast cancer, reviewed in." (PMID 37275275, 2023). "The diagnostic value of FTO, PIK3CB, CEA and CA15-3 in breast cancer was evaluated by constructing ROC curves." (PMID 37861518, 2023). "Exosomal circ_0001142 from breast cancer (BC) is released into macrophages, inducing M2 polarization and interfering with autophagy by targeting the miR-361-3p/PIK3CB pathway under the condition of endoplasmic reticulum (ER) stress." (PMID 37365670, 2023). "In particular, homologs AKT1, AKT2, ERBB2, FGFR2, and PIK3CA in CGC play important roles in breast cancer progression, mediating breast cancer risk, corresponding to the driver candidates RPS6KA1, SGK1, PTK2, IGF1R, PIK3CB, and PRKDC predicted by DriverMP." (PMID 38091511, 2022). "Circ_0001142 carried by breast cancer cell-released EVs influences macrophages’ autophagy and polarization via circ_0001142/miR-361-3p/PIK3CB pathway." (PMID 36405712, 2022).
breast cancer (continued). "p110α RNAi inhibited growth and promoted apoptosis in all tested estrogen receptor positive (ER+) breast cancer cells under estrogen-deprived conditions, whereas p110β RNAi only affected cells harboring PIK3CB amplification." (PMID 34769309, 2021). "In hormone-regulated cancers such as prostate and breast cancer, activation of the PI3K pathway is often driven by mutations/amplification/overexpression of PIK3CA/PIK3CB, or loss of the tumor suppressor PTEN3–6." (PMID 34417459, 2021). "The PI3K pathway undergoes many changes in breast cancer caused by mutations or amplifications of genes which encode the catalytic subunits p110α (PIK3CA) and p110 β (PIK3CB), but also the regulatory subunit PI3K, p85α (PIK3R1)." (PMID 33375317, 2020). "The analogous analysis of the breast cancer subset of the MSK-IMPACT study found that mutations in both STK11 and PIK3CB tended to be mutually exclusive with PTEN mutations, but was not statistically significant." (PMID 29566768, 2018). "Increased expression of PIK3CB was associated with decreased overall survival, and relapse-free survival in HER 2+ breast cancer patients." (PMID 27792127, 2016). "Mutations in the PI3K/AKT/mTOR pathway are frequent in breast cancer, and activation of this pathway via molecular aberrations in PIK3CA, PIK3CB, PIK3R1, AKT, TSC1/2, and PTEN promotes resistance to HER2-targeted therapies." (PMID 27923043, 2016). "Thus, the inclusion of FTO and PIK3CB in the diagnostic panel can enhance the diagnostic effectiveness of CEA and CA15-3 in breast cancer." (PMID 37861518, 2023). "Moreover, the combination of FTO, PIK3CB, CEA, and CA15-3 exhibited an improved diagnostic value for breast cancer compared to the use of CEA or CA15-3 alone." (PMID 37861518, 2023). "Moreover, AZD8186 is currently used in combination with docetaxel to treat patients with metastatic or unresectable PTEN- or PIK3CB-mutant advanced solid tumors, including breast cancers (NCT03218826)." (PMID 36671478, 2023). "Combining FTO, PIK3CB, CEA and CA15-3 improves the diagnostic efficiency of breast cancer." (PMID 37861518, 2023). "PIK3CA, PIK3CB and PIK3R1 mutations are frequently detected in breast cancer." (PMID 36010585, 2022). "Nevertheless, the effects of brazilin on PIK3CB in metastatic breast cancer cells remain unclear." (PMID 32986377, 2020). "In early-stage breast cancer (I + II), the combination of FTO, PIK3CB, CEA and CA153 yielded an AUC of 0.895, sensitivity of 77.22% and specificity of 85.71%." (PMID 37861518, 2023). "According to recent cancer genomic sequencing efforts, PIK3CA alterations are found in more than 30% of breast cancers, and PIK3CA/PIK3CB alterations are observed in 15% of prostate cancers." (PMID 34417459, 2021). "Breast cancer patient data were used to assess the clinical relevance of PIK3CA and PIK3CB in patients." (PMID 27792127, 2016). "Therefore, we assessed the diagnostic value of fat mass and obesity-associated protein (FTO), phosphatidylinositol-4,5-biphosphate 3-kinase catalytic subunit β (PIK3CB) as a potential complementary biomarker to CEA and CA153 in breast cancer by measuring serum FTO,PIK3CB levels." (PMID 37861518, 2023). "In addition, we did not investigate the prognostic value of FTO,PIK3CB on breast cancer, so we hope to explore the prognostic significance of FTO,PIK3CB on breast cancer in subsequent experiments." (PMID 37861518, 2023).
prostate carcinoma (13 papers, 2013 to 2025). A carcinoma that arises from epithelial cells of the prostate gland. "Thus, miR-34a-5p/HIF1A, miR-34a-5p/IGFBP2 and miR-34a-5p/PIK3CB, as well as Axl, could represent possible biomarkers and therapeutic targets for prostate cancer; conversely, miR-34a-5p upregulation is associated with the development of AD." (PMID 35741059, 2022). "miR-34a-5p downregulation in prostate cancer is responsible for the overexpression of HIF1A, IGFBP2 and PIK3CB, associated with tumor development and progression." (PMID 35741059, 2022). "In human prostate cancer, mutations and inactivation of Pten are more common than amplifications and activation of PIK3CA, PIK3CB, PIK3R1, and AKT1." (PMID 36358740, 2022). "Of note was PI3K family members: PIK3C2G, PIK3CA, PIK3CB, PIK3R4, Mucin family members: MUC1, MUC4 and MUC6 and other prostate cancer associated genes such as SMAD4, SOX9 and SPOP7,9,40,41." (PMID 32796921, 2020). "Of interest, KIN-193 is a drug targeting the PIK3CB protein and under investigation for the treatment of breast and prostate cancers." (PMID 23365759, 2013). "Taken together, we have demonstrated that aberrant PI3K signaling driven by amplification or activating mutations of PIK3CA or PIK3CB are able to shift p110 isoform dependency regardless of PTEN status across multiple prostate cancer models." (PMID 34417459, 2021). "Here, the authors show that gain-of-function mutations in PIK3CA or PIK3CB can confer PI3K p110 isoform dependency and that the direct inhibition of AKT may be superior to PI3K inhibition in PTEN-deficient prostate cancers." (PMID 34417459, 2021). "Moreover, PIK3CB mutation and amplification is significantly enriched in tumors with FOXP1-SHQ1 deletion (P = 0.002, Fisher’s exact test) in the TCGA prostate cancer cohort, which has available exome sequencing data." (PMID 29057879, 2017). "The upregulated gene set included oncogenes such as PIK3CB, FGFRL1, and NCOA2; prostate cancer-related genes such as SPON2, PCAT4, and SCHLAP1; and cell cycle genes such as MKI67, MCM4, KIF4A, CENPF, and FLNB." (PMID 38067373, 2023).
glioblastoma (12 papers, 2016 to 2024). The most malignant astrocytic tumor (WHO grade IV). "Knockdown of PIK3CB (encoding p110β) suppresses cell proliferation and induces apoptosis in ovarian cancer and glioblastoma in vitro and in vivo, suggesting p110β plays important roles in cell growth." (PMID 27176481, 2016). "Constitutive G protein signalling may provide an explanation as to why PIK3CA mutations are relatively common in glioblastoma (9% in the TCGA database) while PIK3CB mutations are rare (1% in the TCGA database)." (PMID 28051998, 2017). "Our study has revealed novel mechanistic insights into Cx43/PI3K-mediated temozolomide resistance in glioblastoma and demonstrated that targeting Cx43 and PIK3CB/p110β together is an effective therapeutic approach for overcoming chemoresistance." (PMID 35022385, 2022). "Restoring PTEN in glioblastoma cells or knocking down PIK3CB can significantly downregulate the phosphorylation of AKT, inhibit cell proliferation, block the cell cycle, and promote apoptosis in the G0/G1 phase." (PMID 36065261, 2022). "Inhibition of PIK3CB with a specific inhibitor, reduced cell viability, and proliferation in glioblastoma." (PMID 32986377, 2020). "Recent studies implicate overexpression of the PIK3CB/p110β isoform in glioblastoma, where it acts as a selective tumor survival factor." (PMID 32946518, 2020). "This preferential activation of PIK3CB/p110β results in sustained cell survival, which promotes glioblastoma progression by inducing drug resistance and leading to tumor recurrence." (PMID 29326882, 2017). "These details at the molecular level will shed light on the design and production of PIK3CB/p110β-selective inhibitors with stronger inhibition of glioblastoma and less toxicity to normal brain tissues." (PMID 29326882, 2017). "Given this low cytotoxicity to normal astrocytes, selectively targeting PIK3CB/p110β is expected to have minimal side effects, thereby representing an appealing approach in treating glioblastoma." (PMID 29326882, 2017). "Through exploring the relationship of these candidates with glioblastoma recurrence using the TCGA patient data, we found that high levels of PIK3CB mRNAs correlated with high incidence and poor survival of glioblastoma recurrence." (PMID 29326882, 2017). "PIK3CB has been reported as a selective survival factor in glioblastoma." (PMID 32419250, 2020). "Herein, we speculate that GPCRs preferentially activate PIK3CB/p110β, but not other PI3K catalytic subunits, in glioblastoma expressing high levels of PIK3CB/p110β." (PMID 29326882, 2017).